JAG2 (jagged canonical Notch ligand 2)
Diseases named in the same sentence as JAG2 in open-access papers (continued):
Sharing a sentence is not in itself a finding about the gene and the disease.
microtia (1 paper, 2025). "Certainly, the current results are insufficient to prove that JAG2 is a pathogenic gene of microtia, and further investigation is still needed." (PMID 40433419, 2025). "Although the current results are insufficient to fully prove that JAG2 is a pathogenic gene of microtia and further investigation is still needed, this study provides detailed insight into the pathogenesis of microtia." (PMID 40433419, 2025). "Therefore, JAG2 is a potential prenatal diagnostic marker for non-syndromic microtia." (PMID 40433419, 2025). "We speculated that considerable upregulation of JAG2 might cause functional deficit of mature chondrocytes or impair the differentiation of chondrocyte progenitor cells by activating the Notch signaling pathway, and eventually lead to the occurrence of congenital microtia." (PMID 40433419, 2025). "We identified JAG2 as a prominent biomarker for microtia, evidenced by its significant upregulation in microtia cartilage." (PMID 40433419, 2025). "This prominence of JAG2 strongly suggests its potential role as a biomarker for microtia." (PMID 40433419, 2025). "Through the utilization of integrative bioinformatics, we find that JAG2 may play an important role in the pathogenesis of microtia." (PMID 40433419, 2025). "The up-regulation of JAG2 may affect the maturation and differentiation of chondrocytes by activating Notch signaling, which eventually leads to the occurrence of microtia." (PMID 40433419, 2025). "Our findings implicate JAG2 in microtia development and suggest its role in chondrocyte maturation and differentiation through Notch signaling pathway activation, shedding light on the potential pathogenesis of microtia." (PMID 40433419, 2025). "Although JAG2’s role in the development of microtia has not been previously reported, the Notch signaling pathway is known to be involved in chondrocyte hypertrophy and differentiation." (PMID 40433419, 2025).
Obesity (1 paper, 2015). Accumulation of substantial excess body fat. "We can hypothesize that JAG2 expression could be regulated in cis in other tissues to influence obesity in chicken because JAG2 is expressed in many tissues, or that the age of birds we analyzed is irrelevant if there is any impact of developmental state on JAG2 expression." (PMID 25653314, 2015).
oral squamous cell carcinoma (1 paper, 2020). "In the present study, we aimed to unveil the relation of JAG2 expression and clinicopathological features in oral squamous cell carcinoma (OSCC)." (PMID 32250571, 2020).
renal carcinoma (1 paper, 2020). A carcinoma arising from the epithelium of the renal parenchyma or the renal pelvis. "We found knockdown of UCA1 increased DLL1, Jag1, Jag2 and Notch1expression and decreased DLL4, NICD and Hes1 expression of renal cancer cells in vivo." (PMID 31996265, 2020). "Knockdown of UCA1 increased DLL1, Jag1, Jag2 and Notch1expression and decreased DLL4, NICD and Hes1 expression in renal cancer cells." (PMID 31996265, 2020).
skin tumours (1 paper, 2014). "We investigated Notch pathway activity in skin tumours from patients with germline mutations in CYLD and found that JAG2 protein levels and Notch target genes were upregulated." (PMID 25565632, 2014).
tongue cancer (1 paper, 2020). A malignant neoplasm affecting the tongue. "An earlier study demonstrated that JAG2 expression was highly correlated in tongue carcinoma tissues." (PMID 32250571, 2020).
uterine cancer (1 paper, 2022). Primary or metastatic malignant neoplasm involving the uterine corpus and/or the cervix. "Expression alterations of NOTCH2, NOTCH3, NOTCH4, JAG2, and HES1 were evaluated as independent and significant prognostic factors for uterine cancer patients." (PMID 35136410, 2022). "NOTCH2, NOTCH3, NOTCH4, JAG2, and HES1 may be used as independent and significant prognostic factors for uterine cancer patients." (PMID 35136410, 2022).
tumor (62 papers, 2014 to 2025). "Instead, we were interested to assess if Jag2 exposure would alter the phenotype of primary tumor cells causing them to become more similar to their metastatic counterparts." (PMID 37202533, 2023). "JAG2 expression on tumour cells was significantly associated with mucinous (p = 0.044) and LVI (p = 0.038) and NME2 were significantly correlated with histological grade and LVI at p = 0.032 and p = 0.048 respectively." (PMID 30679934, 2019). "In contrast, our findings showed that expression of JAG2 on tumour cells significantly associated with histological type of tumour, and vascular invasion." (PMID 30679934, 2019). "To determine if this finding was relevant in a human model, we assessed JAG2 expression in CYLD defective tumour lysates, obtained from patients with germline CYLD mutations." (PMID 25565632, 2014). "Besides, the increased expression of JAG2 is associated with hypoxia and the increased expression of JAG2 on tumor cells can promote the tube formation of endothelial cell, indicating the involvement of JAG2 in angiogenesis." (PMID 31217907, 2019). "JAG2+TANs are closely linked to IL-8-driven immune evasion microenvironment and may serve as a promising therapeutic target for the reinvigoration of anti-tumour immunity." (PMID 32778818, 2020). "A genomic analysis of the Notch pathway in 16 glioma tumor-initiating cell populations identified genes such as NOTCH1, NOTCH3, MAML1, JAG2, HES1, and DLL-3, which were associated with active Notch signaling and enriched in tumors responsive to treatment." (PMID 40003637, 2025). "When the Notch pathway is suppressed by an inhibitor, such as a γ‐secretase inhibitor, treatment with an anti‐JAG2 antibody results in the attenuation of tumor growth and augmentation of cytotoxic roles of CD8+ T cells." (PMID 38491819, 2024). "In summary, we observed an inverse relationship between NOTCH1 and NOTCH3 levels and cisplatin responsiveness, overall protective effects by CAFs, and a potential link between JAG2 expression with tumor cell survival." (PMID 38001580, 2023). "We observed that JAG1 and JAG2 showed potential as therapeutic targets in MM, as their silencing resulted in a reduction in the tumor burden." (PMID 37834003, 2023). "The expression levels of human JAG2 in U266 cells isolated from BM samples of xenografted mice showed a statistically significant correlation with the amount of tumor cells, their proliferation index and the levels of NOTCH activation." (PMID 37834003, 2023). "In ovarian tumor, CXCL8 promotes the recruitment of tumor associated neutrophils in TME and activates JAG2 in tumor-associated neutrophils, which, in turn, suppresses the activity of the CD8+ T cells." (PMID 36091114, 2022). "A particularly interesting potential interaction with high relevance for tumor biology includes JAG2 (cancer) with NOTCH3 (mouse stroma), and interactions of integrins (ITGA2, ITGA2B) with ECM proteins (COL2A1, LAMA1)." (PMID 35053442, 2022). "Next, we evaluated the roles of both Jag1 and Jag2 in CSC induction by inhibiting Notch signaling with Jag1 and Jag2 blocking antibodies in the tumor cell-macrophage co-culture assay." (PMID 34911937, 2021). "EOC tumour tissue conditional cultural medium (TTCM) significantly upregulated JAG2 expression in neutrophils compared with the control medium." (PMID 32778818, 2020). "As our expectation, the protein expressions of Jagged2, Notch, MMP-2/MMP-9 and PI3K/AKT/mTOR signaling were significantly reduced by Mel treatment and further significantly reduced by silenced Notch/JAG2 in the harvested tumor mass." (PMID 32792862, 2020). "Notch pathway blocked using γ-secretase inhibitor LY3039478 and anti-JAG2 antibody led to retarded tumour growth and augmented cytotoxic effects of CD8+ T cells." (PMID 32778818, 2020).
tumor (continued). "To evaluate the roles of Notch ligands DLL1 and Jag2 expression on DCs in the regulation of T-cell-mediated anti-tumor immunity, we generated mice with CD11c-lineage-specific deletion of their genes." (PMID 30940183, 2019). "Proteins, HLAB, ADAMTS2, LTBP3, JAG2 and NME2 were significantly associated with tumor progression, vascular invasion and distant liver metastasis." (PMID 30679934, 2019). "Expression of HLAB, protein 14-3-3β, LTBP3, ADAMTS2, JAG2 and NME2 on tumour cells was significantly associated with clinical parameters related to tumour progression, invasion and metastasis." (PMID 30679934, 2019). "Six of the 10 (60%) proteins examined using TMA immunohistochemistry, HLAB, protein 14-3-3β, LTBP3, ADAMTS2, JAG2 and NME2, were significantly associated with clinical parameters which have shown to relate with tumor progression, invasion and metastasis." (PMID 30679934, 2019). "Ectopic expression of JAG2 resulted in a significant increase in tumor size, suggesting that JAG2 enhances tumorigenicity of MC38 cells." (PMID 28881809, 2017). "The increased expression of JAG2 in CYLD defective tumours in particular supported our in vitro findings that CYLD-MIB2 regulation of Notch signalling influences expression levels of the ligand JAG2." (PMID 25565632, 2014). "Notably, genes such as PLAC8 and the Notch ligand JAG2 were significantly upregulated, while tumor suppressors, like SMARCB1, showed marked downregulation." (PMID 41595423, 2025). "Finally, the analysis found that in the TCGA CRC and GSE110224 datasets, the expression of JAG2 in the tumor samples was significantly higher than that in the normal sample group (P < 0.05)." (PMID 38369589, 2024). "We initially expected that JAG2 expression might correlate with decreased cell viability and increased tumor cell death, but further research is needed to confirm this." (PMID 38001580, 2023). "This jag2-mediated NK cell activation was important for reducing tumor size in vivo and this activation could be inhibited by using a GSI against Notch." (PMID 38269089, 2023). "Interestingly, tRF/miR-1280 reduces tumor formation and metastasis by directly targeting the Notch ligand JAG2, which is essential for cancer stem-like cells (CSC) in CRC progression." (PMID 35035608, 2022). "It has been reported that Jagged-2 (JAG2) can bind to Notch2 and stimulate tumor proliferation." (PMID 33920054, 2021). "Consistently, the anti-JAG2 antibody also significantly inhibited tumour growth in vivo." (PMID 32778818, 2020). "Expression of HLAB, ADAMTS2, LTBP3, JAG2 and NME2 on tumour cells, was associated with tumour progression and invasion, metastasis and CRC specific survival may serve as potential biomarkers to stratify CRC patients into low and high risk of tumour metastasis." (PMID 30679934, 2019). "In addition, elevated levels of JAG2 result in significant chemoresistance, and when JAG2 is knocked down in mice, tumor cells become sensitive to chemotherapeutics (doxorubicin)." (PMID 30679932, 2019). "Strong expression of JAG2 in tumour cells correlated with good CRC specific survival." (PMID 30679934, 2019). "In contrast, deletion of both alleles of Jag2 did not result in major alteration in LLC tumor growth." (PMID 30940183, 2019). "Additionally, JAG2 has been shown to be a promising target in several cancer cell lines, as specific antibody–drug conjugates have resulted in tumor reduction." (PMID 30679932, 2019). "Studies have shown that JAG2 promotes tumor cell metastasis in various tumors." (PMID 31198409, 2019). "Our study suggests a novel role of JAG2 in tumor resistance to chemotherapy." (PMID 28881809, 2017). "Interestingly, metastatic cells cultured on Jag1 expressed higher levels of Hes1, a target gene that has high expression in cells derived from the primary tumors, while exposure to Jag2 increased expression of Hey1 in both primary tumor and metastasis-derived cells." (PMID 37202533, 2023).
tumor (continued). "However, whether the epigenetic regulation of E-cadherin and Vimentin would affect the regulatory pathway of JAG2 and tumor metastasis and the universality of JAG2 related pathways are still worthy of further exploration." (PMID 31198409, 2019). "Also, whether the biological function of JAG2 exhibited in the form of exosomes can be extrapolated to other tumor cells remains unknown." (PMID 31198409, 2019). "Yang’s research highlights IL-8’s role in TANs recruitment and JAG2 expression, and the blockade of CXCR2 signaling reduces tumor growth and TANs numbers while enhancing CD8+ T cell activity." (PMID 40160822, 2025). "Also, TRIP6 may promote angiogenesis in tumor cells by promoting the expression of JAG2." (PMID 38369589, 2024). "It has been described a dual role for the Notch receptor (Notch 1–4)-ligand (JAG1, JAG2, DLL1, DLL3 and DLL4) pathways as oncogenic or tumor suppressors." (PMID 36745330, 2023). "We observed a clear decrease in the JAG2 level after cisplatin exposure, which correlated with the WST-8 viability test results for both 3D monocultures and cocultures of both tumor cell lines." (PMID 38001580, 2023). "Bone marrow-derived CD11b+JAG2+ cells infiltrate primary colorectal tumors and initiate the EMT program of tumor cells, thus promoting tumor metastasis." (PMID 35332121, 2022). "We found that silencing of JAG2 suppresses the growth of CRC xenografts, while its over-expression increases tumor growth." (PMID 28881809, 2017). "JAG1, JAG2, HEY1 and HES1 had relatively higher expression in tumor samples compared to the pool of normal controls." (PMID 28146432, 2017). "We have previously shown that JAG2 is upregulated in CYLD defective tumour tissue, particularly in “Wnt active” tumours." (PMID 25565632, 2014). "On the other hand, a subset of MBs, and/or a subset of cells within a given tumor, express high levels of MYC and acquire a concomitantly increased JAG2 protein level, which likely alters the fine-tuned NOTCH signaling cascade." (PMID 24708907, 2014). "There was no significant differential expression of DLL3 and JAG2 between different tumor stages; however, tumors with higher grades showed significantly higher expression of DLL3 (grade III vs. grades I, II; P value < 0.0001)." (PMID 36476410, 2022). "In contrast to the striking effect of Dll1 deletion on IFN-γ production, genetic ablation of Jag2 in DCs did not have a major effect on the number of tumor-infiltrating IFN-γ-producing cells." (PMID 30940183, 2019). "Similarly, elevated levels of JAG2 and NOTCH4 in TNBC could further sustain Notch signaling, promoting aggressive tumor behavior and therapy resistance." (PMID 41463075, 2025). "Together, the concurrent elevation of NOTCH4 and JAG2 supports sustained Notch signaling across diverse tumor subtypes, which in the case of JAG2 may be additionally related to the lack of inhibitory action by miRNAs." (PMID 41463075, 2025). "For example, Jag2 regulates tumor cell proliferation and migration via the Notch signaling pathway." (PMID 41268436, 2025). "In contrast, Jag2 is significantly elevated in metastatic cells compared to those derived from the primary tumors, and in UT-SCC-54C and UT-SCC-74B (metastatic) cells reach ~4-fold and ~6-fold higher expression than their corresponding primary tumor derived counterparts." (PMID 37202533, 2023). "Quantitative RT-PCR analysis revealed that the average expression of JAG2 mRNA in tumor tissues was ∼7 fold higher as compared to normal epithelium while the mRNA expression of other NOTCH ligands was not significantly different between tumor and normal epithelium." (PMID 28881809, 2017). "In our study, Jag2 deletion in DCs did not result in any major changes in anti-tumor T-cell responses, such as IFN-γ production but had a negative effect on the number of IL-4 producing cells, consistent with the role of Jag2 in supporting Th2 differentiation." (PMID 30940183, 2019).
cancer (53 papers, 2008 to 2025). A tumor composed of atypical neoplastic, often pleomorphic cells that invade other tissues. "tRF/miR-1280 binds to and inhibits the expression of the downstream target gene of the Notch pathway, JAG2, which results in the loss of stemness in cancer cells and a reduction in the number of cancer cells with EMT phenotypes, thus inhibiting the growth and metastasis of CRC." (PMID 40265011, 2025). "Previous studies have highlighted the role of Jag2 in various diseases, including cancer and cardiovascular diseases." (PMID 41268436, 2025). "In addition, about 30% of HNSCC or skin cancer cases show overexpression of JAG1 or JAG2, which may be in line with the activation of the Notch pathway at least in some cases, especially aggressive, late-stage cancers, and is associated with poor patient outcome." (PMID 37760535, 2023). "Understanding the activation of Jag2 by hypoxia will provide relevant avenues for therapies targeting Jag2 in both cancer cells and stroma." (PMID 38269089, 2023). "JAG2 is a transmembrane ligand of the Notch receptor and up-regulated activates the cancer-related Notch signaling pathway." (PMID 36439446, 2022). "RCC tissues that successfully generated organoids highly expressed genes associated with stemness (WNT6/11, FZD8/9 and JAG2), cell matrix (MMP2, COL1A1), fatty metabolism (ACOT2, LIPE) and cancer development (TGFB1, SMAD6/7, EGF and FGF1)." (PMID 35802820, 2022). "By contrast, JAG2 immunoreactivity was found in 31 of the 91 invasive cancer cell samples at the invasion front." (PMID 32250571, 2020). "The present findings suggest that JAG2 overexpression, especially at the cancer invasion front, has potential prognostic value." (PMID 32250571, 2020). "The present result indicated that JAG2 was expressed in cancer invasion front of 31 of 91 OSCC tissue specimens." (PMID 32250571, 2020). "Within cancer, Notch signaling mediates hypoxia, invasion, and chemoresistance, and JAG2 expression in primary tumors has been correlated with vascular development and angiogenesis." (PMID 30679932, 2019). "These indicates that JAG2 is increased in middle stage to promote the angiogenesis and invasion ability of cancer cells." (PMID 31217907, 2019). "Furthermore, they demonstrated that increased JAG2 expression in bone marrow stroma contributes to the growth of cancer stem-like cells." (PMID 41463075, 2025). "INHBA and JAG2 both expressed more in carcinoma tissues than that in adjacent tissues." (PMID 34103052, 2021). "Overexpression of JAG2, largely in cytoplasm in a part of OSCC at cancer invasion front, might be linked to the novel molecular mechanism, which was responsible for oral carcinogenesis at relative young age." (PMID 32250571, 2020). "Regulation of Notch signaling by the tumor architecture, in this case the activation of HEYL transcription by JAG1 and JAG2 expression in neighboring cells, is also observed in other types of cancers, such as basal cell carcinoma and might be an important criterion in CRC." (PMID 37860822, 2023). "In addition, in supratentorial (ST) EPN, NOTCH1 expression was associated with cancer stem cell (CSC) markers, VEGFA and L1CAM, and the ST_EPN_RELA subtype showed the activation of selected key members of the Notch signaling pathway (NOTCH1, JAG1, JAG2, HES4)." (PMID 36293188, 2022). "However, the prognostic value of JAG2 expression depends on the cancer type." (PMID 32250571, 2020). "This indicates that JAG2 could be a practical therapeutic target for various cancers." (PMID 32250571, 2020). "The level of APH1A, CTBP1, HEY1, HEY2, JAG2, NOTCH4 was significantly higher in cancer samples compared to the control group, while the concentration of DTX1 TLE2, TLE4 was below the detection threshold." (PMID 41463075, 2025). "Mutations in Notch ligands are found more rarely in the same cancers, ranging only between 0.5 and 3% for DLL1, DLL3, DLL4, JAG1, or JAG2." (PMID 37760535, 2023).